AKT1 (AKT serine/threonine kinase 1)
Diseases named in the same sentence as AKT1 in open-access papers (continued):
Sharing a sentence is not in itself a finding about the gene and the disease.
tumor (continued). "Concurrent ablation of Akt1 rescued the tumor growth induced by PTEN deficiency." (PMID 38675376, 2024). "Nonetheless, few investigations in recent decades have searched for mutations in other genes, such as CDKN2A, PTEN and AKT1, which could provide more knowledge regarding this tumor’s resistance and etiopathogenesis." (PMID 37368773, 2023). "AKT1 alterations were poorly detected in our cohort and were obtained in only in 1.4% of samples (1/70).AKT1 E17K mutation was found in a man with pT1 stage and high-grade tumour." (PMID 35317488, 2022). "AKT1 deficiency suppressed the mechanism of AKT signaling, inhibiting tumor progression and onset." (PMID 36286049, 2022). "As the disease progresses from androgen-dependent to castrate-resistant, a decrease in both MST1 and PTEN tumor suppressor levels enhances AKT1 activity, thus linking MST1 loss with the phosphoinositide 3-kinase/protein kinase B (PI3K/AKT) pathway activity in driving disease progression." (PMID 35954292, 2022). "Activating mutations of PI3K and its catalytic subunit alpha (PIK3CA) are associated with co-alterations of PTEN, MAPK and AKT1, which are sufficient to foster tumorigenesis, tumor growth, migration, protein synthesis and glucose metabolism in pre-clinical models." (PMID 34830902, 2021). "Pretreatment tumor molecular profiling demonstrated an AKT1 E17K mutation." (PMID 34407844, 2021). "Our analysis identified the AKT1 E17K mutation as the putative driver of the tumor." (PMID 34885114, 2021). "Mutations with high VAFs indicated early appearance during tumorigenesis or tremendous contribution to later expansion of tumor cells, and the previous study demonstrated AKT1, CBFB, MAP2K4, ARID1A, FOXA1, and PIK3CA mutations have relatively high average VAFs in breast cancers." (PMID 33173047, 2020). "The fact that patients whose tumours carry an AKT1-E17K mutation have shown high response rates following treatment with the ATP-competitive-inhibitor-capivasertib suggests that, in a subset of patients, this mechanism of AKT activation can render tumours susceptible to AKT kinase inhibition." (PMID 32453400, 2020). "As signal transduction pathways initiated by integrin α2β1 are not well understood, the present study seeks to demonstrate that integrin α2β1 can be implicated in the protection of tumor cells from anoikis through the inhibition of Akt1, one of the Akt kinase izoforms." (PMID 30956761, 2019). "Genetic analyses revealed additional mutations that could promote tumor cell growth despite the inhibition of AKT1/2." (PMID 31835495, 2019). "The RAS/MEK/ERK and PI3K/AKT1 pathways, although they are generally associated with proliferation and survival respectively, are also interconnected to modulate several cellular mechanisms involved in tumour development and progression." (PMID 28880250, 2017). "Studies have shown that there is an association between AKT1 activation and tumor aggressiveness." (PMID 28117295, 2017). "This cannot be ensured for human tumours with Akt1-mutations for which ”controls” may be impossible to find." (PMID 28209968, 2017).
tumor (continued). "Furthermore, RPPA analyses demonstrated differential gene expression and activation signatures in mTOR signaling pathway components between tumor samples with activated AKT1 versus Pten loss." (PMID 27598148, 2016). "Second, the selective advantage of tumor cells may involve interactions of the mutated AKT1 with ovarian-specific (signaling or interacting) partners." (PMID 26137586, 2015). "Another explanation for having metastasis in tumours with active Wnt pathway might be the involvement of another mutation that affects the akt1 or the akt2 gene." (PMID 26528548, 2015). "Since expression of E7 reflects tumour progression, these findings suggest that AKT1 loss associated with episomal HPV16 may have positive prognostic implications in vulval malignancy." (PMID 22685591, 2012). "Furthermore, an oncogenic hotspot mutation in the pleckstrin homology domain (PHD) of AKT1 is present in several tumor entities, albeit at a lower frequency than PIK3CA mutations." (PMID 22363598, 2012). "AKT1 deficiency delayed tumor growth and reduced metastasis." (PMID 20174572, 2010). "A few oncogenes (e.g. phosphatidylinositol 3-kinase, activated AKT1) inhibit autophagy, while numerous tumor suppressors (e.g. BH3-only proteins, death-associated protein kinase-1, PTEN, tuberous sclerosic complex 1 and 2, TSC1 and TSC2 and LKB1/STK11) induce autophagy." (PMID 21191146, 2010). "The finding of this recurrent AKT1 mutation in various tumours suggests that AKT may be an attractive therapeutic target for some patients." (PMID 18611285, 2008). "In vivo studies indicated that Akt1-E17K mutation may induce mammary hyperplasia that can eventually lead to lung epithelium disorder in mouse models thereby indicating their oncogenic role in initiation and development of tumor." (PMID 40176859, 2025). "Indeed, while the inhibition of Akt1 was significantly linked to the reduced proliferation and tumor progression of in vivo OC cells, the silencing of Akt2 increased the tumor growth, and Akt3-KO mice displayed an intermediate phenotype, leaning towards the stimulation of OC cell growth." (PMID 38929705, 2024). "Notably, compared to AKT1-WT, AKT1-R391K mutation significantly retarded tumor growth." (PMID 34103528, 2021). "Especially patients with an AKT1 mutated tumor could benefit from AKT1 inhibition by capivasertib." (PMID 34885114, 2021). "Davies found that AKT1 (E17K) mutations were effective therapeutic targets for AKT inhibitors, although combinations with other targeted agents may be required where activating oncogenic mutations of other proteins were present in the same tumour." (PMID 31895688, 2020). "However, together with the fact that not all AKT-mutant tumours were responsive to AKT inhibition, these data suggest that additional contextual information (i.e. biomarkers) will be needed to better predict when the AKT1-E17K mutation can identify responsive tumours." (PMID 32453400, 2020). "Because overexpression of Myr-Akt1 in GSCs expressing shWISP partially rescued the impaired tumor growth caused by WISP1 disruption, we speculated that other mechanisms may be involved in the growth of GBMs promoted by WISP1, in addition to its autocrine signaling in GSCs." (PMID 32541784, 2020).
tumor (continued). "Our Protein–protein interaction (PPI) network analysis results demonstrated that the key target genes of FSH for anti-tumor treatment were AKT1, EGFR, BCL2, CTNNB1 and HSP90AA1." (PMID 40230723, 2025). "Its role in metabolic reprogramming, particularly via phosphorylation‐induced cytoplasmic retention of ME2 and assembly of glycolytic enzyme complexes, represents a novel and critical mechanism by which Akt1 supports the bioenergetic demands of tumor cells." (PMID 40798865, 2025). "These Akt2-OE CTLs showed a greater capability to proliferate, to release cytokines and to kill tumor cells in comparison with Akt1-OE or control CTLs." (PMID 40139836, 2025). "Specifically, AKT1 inhibited the protein lipoylation by phosphorylating FDX1 while simultaneously regulating tumor metabolic reprogramming, ultimately suppressing cuproptosis." (PMID 39976173, 2025). "Hyperactivation of AKT1 is commonly observed in various malignancies, including OC, and contributes to tumor cell resistance to apoptosis and enhanced invasiveness." (PMID 40933552, 2025). "Specifically, miR-149-5p affects the expression level of AKT1 in several GC cell lines, thus promoting tumor growth." (PMID 41515889, 2025). "NF2 mutations occur in all grades and AKT1 E17K and KLF4 K409Q often co-occur with TRAF7 mutations predominantly in grade 1 tumours." (PMID 40420192, 2025). "In four patients, longitudinal analysis of subsequent lesions highlighted an increase in mutations, like missense or splice variants in the PMS2, SMARCA4, ARID1A, AKT1, BMPR1A, and PTEN genes, suggesting tumor evolution." (PMID 41514647, 2025). "The PTEN tumor suppressor regulates the PIK3CA/AKT1 pathway, and its inactivation significantly contributes to tumorigenesis and progression in hormone receptor-positive/HER2-negative (HR + /HER2 −) metastatic breast cancer (MBC)." (PMID 40931235, 2025). "The protein kinase B 1 (AKT1) pathway, for instance, is frequently overexpressed in tumor cells and TAMs, promoting invasion, metastasis, and epithelial–mesenchymal transition (EMT)." (PMID 40553053, 2025). "By IHC staining, we found that STOX1‐A, cyclin B1, and p‐AKT1 (Ser473) were all predominantly expressed in the nucleus of tumor cells." (PMID 40567110, 2025). "AKT1 mutations were more prevalent in intermediate and advanced HCC stages, suggesting a role in tumor progression." (PMID 41291320, 2025). "Its phosphorylation at Ser473 facilitates epithelial-mesenchymal transition, while EBV-LMP1 enhances cyclophilin A/AKT1 interactions to promote tumor progression." (PMID 40607002, 2025). "Within this pathway, AKT1 operates as a pivotal upstream regulator of the transcription factor RUNX2, a key effector implicated in tumor progression and species, highlighting its potential as a translational target." (PMID 40862758, 2025). "The F‐LAN‐RX‐0201 exhibited promise as a therapeutic agent for tumor cells with greater folate‐receptor expression, with improved cellular uptake, Akt1 inhibition, and in vivo tumor inhibition." (PMID 40874416, 2025). "Mice injected with GRP78-overexpressing HCC1806 cells developed multiple metastatic nodules on the lung surfaces, an effectively attenuated by MK2206 treatment, indicating that AKT1 activity is critically for GRP78-mediated tumor metastasis." (PMID 40223122, 2025). "As tumor cells proliferated rapidly, the tumor Ag load increased, repeatedly stimulating Akt1-OE CTLs and triggering NFAT pathway activation." (PMID 40139836, 2025). "The ZAXL:239 affibody significantly reduced cell viability and inhibited tumor proliferation by inhibiting the phosphorylation levels of the PI3K/AKT1 and MEK/ERK pathway in mice model." (PMID 39644434, 2025). "Mechanistically, we demonstrate that CYPJ interacts with AKT1 and inhibits the PI3K-AKT signaling pathway, which leads to polarization of TAMs toward the anti-tumor M1 phenotype, resulting in a tumor-suppressive effect." (PMID 40520002, 2025).
tumor (continued). "Hyperactivation of the PI3K/AKT/mTOR pathway occurs in approximately 35–50% of TNBC cases, primarily driven by activating mutations in PIK3CA (15–25%) and AKT1 (5–10%), or the loss of PTEN (30–50%), leading to tumor aggressiveness and therapeutic resistance." (PMID 41516322, 2025). "Akt1 is primarily responsible for the proliferative potential of cells by upregulating Cyclin D1 and S6 and is more highly expressed in the primary BC tumor sample from the breast." (PMID 40080721, 2025). "Compound 17, which exhibited cytotoxicity against PANC−1 cells, was linked to 55 targets, including key targets such as EGFR, AKT1, CDK1, CDK2, MMP9, PIK3CG, and TERT, closely associated with tumour cell proliferation, migration, and apoptosis." (PMID 41006588, 2025). "scRNA-seq revealed compartment-specific target localization: AKT1/ESR1 in tumor cells, SRC/IL6 in myeloid cells, and MTOR/HIF1A across stromal compartments." (PMID 40746726, 2025). "In four patients, longitudinal analyses of subsequent lesions showed the maintenance of most genomic alterations and enrichment in missense or splice variants in PMS2, SMARCA4, ARID1A, AKT1, BMPR1A, and PTEN, indicating the occurrence of tumor evolution." (PMID 41514647, 2025). "In the first‐in‐human clinical trial of the KAT6 inhibitor PF‐07248144, researchers performed preliminary biomarker analyses of circulating tumor DNA (ctDNA) mutation profiling at baseline, including ESR1 and PIK3CA/PTEN/AKT1 genes." (PMID 41357671, 2025). "AKT1 is involved in several biological processes, such as tumor cell migration, cell proliferation, and apoptosis." (PMID 38243957, 2025). "This interaction illustrates a functional axis where miR-30a exerts tumor-suppressive effects by directly targeting AKT1, influencing the downstream transcriptional landscape." (PMID 40862758, 2025). "Previous studies have reported that miR-149-5p functions as a tumor suppressor in HCC by inhibiting the expression of AKT1, MAP2K1, and MTHFR." (PMID 39885395, 2025). "In our model, T cells were stimulated once with target-expressing tumor cells, and p-Akt1 levels were assessed via flow cytometry after 15 min to evaluate downstream signaling activation." (PMID 40181405, 2025). "Inverse effects of rhARSB and ARSB knockdown on phospho(Ser473)-AKT1 indicate that ARSB acts as a tumor suppressor and that a decline in ARSB is pro-oncogenic." (PMID 40562100, 2025). "Tumor- and CRC-specific mutations were mostly synonymous or low-impact variants in genes including AKT1 (YCLO-2), BRAF (YCLO-2), FGFR3 (YCLO-7), and PIK3R1 (YCLO-7)." (PMID 40462147, 2025). "Trials such as NCT02523014 now stratify patients based on SMO, AKT1, and CDK4/6 mutations, to individualize therapy to the tumor’s oncogenic circuitry." (PMID 40867323, 2025). "In neuroendocrine prostate cancer, TACSTD2-driven AKT1 and c-Myc activation enhances lineage plasticity and tumor progression." (PMID 41331197, 2025). "The mutational profile of CRC tumors, including KRAS, NRAS, BRAF, PIK3CA, and AKT1 gene mutation and MSI status significantly influences the characteristics of the tumor microenvironment (TME) and directly impacts patient prognosis." (PMID 40724985, 2025). "To further validate the potential impact of the screened target gene in CC, we selected AKT1—a key gene involved in regulating tumor progression and therapy resistance—for functional verification." (PMID 40487864, 2025). "PTCs harboring BRAFV600E mutations often display concurrent mutations in PIK3CA and AKT1; mutations in the SWI/SNF complex have also been identified in in vivo models coexisting with BRAFV600E mutations, jointly promoting tumor progression." (PMID 41462994, 2025).
tumor (continued). "Targeting AKT1 has been proposed as a promising strategy for reversing chemoresistance and suppressing tumor growth in OC." (PMID 40933552, 2025). "IHC analysis elucidated alterations in intestinal barrier proteins, AKT1/mTOR pathway, and tumor proliferation and apoptosis biomarkers." (PMID 40919243, 2025). "Akt1, a key serine/threonine kinase within this pathway, plays a critical role in tumor progression and the development of therapeutic resistance." (PMID 40798865, 2025). "Akt1, a crucial kinase within this pathway, plays a critical role in tumor progression and the occurrence of therapeutic resistance." (PMID 40798865, 2025). "Histological examination of liver/tumor tissues revealed extensive infiltration of mononuclear cells in tumors of mice receiving Akt2-OE CTLs, while tumors of mice receiving control or Akt1-OE CTLs showed fewer mononuclear cells." (PMID 40139836, 2025). "PIK3CA/AKT1/PTEN tumor alterations were detected in 24 patients (33.8%) receiving capivasertib–fulvestrant and in 22 patients (34.9%) receiving placebo–fulvestrant." (PMID 40346047, 2025). "This distribution suggests that AKT1 mutations are more prevalent in the intermediate and advanced phases of HCC, indicating a potential role of AKT1 in tumor proliferation." (PMID 41291320, 2025). "In PC genetically engineered mouse models, AKT1 is responsible for primary tumor growth, whereas AKT2 promotes the development of distant metastasis and disease aggressiveness." (PMID 39980141, 2025). "VEGFA, in turn, activates the AKT1 pathway, creating a self-reinforcing loop that promotes tumor growth and angiogenesis." (PMID 38666020, 2024). "Breast CSC-derived EVs carry ARRDC1-AS1 to promote breast cancer malignancy by modulating miR-4731–5p/AKT1 axis to foster tumor growth and aggressiveness." (PMID 38962016, 2024). "Current research on HSP90AA1 focuses on its role as a drug target due to its interaction with a variety of tumor-promoting proteins and its role in cellular stress adaptation, including AKT1." (PMID 38927034, 2024). "In BLCA, NAT10 overexpression acetylates BCL9L, SOX4, and AKT1, promoting tumor invasion and metastasis." (PMID 38233930, 2024). "Akt1 is a serine/threonine‐protein kinase that regulates many processes, including proliferation and tumor growth." (PMID 38525111, 2024). "For instance, sulforaphane demonstrates anti-tumor properties by regulating several signaling pathways, such as Nrf2/Keap1, AKT1/HK2, and NF-κB/MMP-9." (PMID 38612546, 2024). "Beyond it, we further stained the tumor sections with AKT-1, HMOX-1 and NRF-2 antibodies to examine their expression." (PMID 39014402, 2024). "The activation of AKT1 contributes to tumor growth by promoting cell survival and resistance to apoptosis, making it a promising target for therapeutic intervention." (PMID 39502516, 2024). "SCP2-specific inhibitors are known to induce autophagy in tumor cells by inhibiting the AKT1-mTOR signaling pathway, thereby suppressing tumor cell proliferation." (PMID 38406279, 2024). "At the molecular level, STK24 phosphorylates AKT1 at Thr21, resulting in the induction of PD‐L1 expression and facilitating tumor immune escape in vivo." (PMID 38229183, 2024). "Blocking the activity of a downstream target of AKT1, mTOR, using rapamycin, inhibited the pro-tumor effects of the fibroblast-derived melanosomes on macrophages." (PMID 38719996, 2024). "AKT1 then inhibits the tumour-suppressor TSC1/2 complex, releasing its inhibition on RHEB, thereby activating mTORC1." (PMID 39568072, 2024). "By modulating the AKT1/mTOR axis, circNRIP1 can change metabolism and autophagy and facilitate tumor spread through exosome communication." (PMID 38192436, 2024). "Serine/threonine kinase 16 (STK16) promotes tumor cell viability and hinders apoptosis through the AKT1 signaling pathway." (PMID 39896803, 2024).